RSPO2 (R-spondin 2)
Diseases named in the same sentence as RSPO2 in open-access papers (continued):
Sharing a sentence is not in itself a finding about the gene and the disease.
tumor (continued). "The aim was to segregate tumours into two clusters: LI tumours with identifiable mutations in APC or CTNNB1 and LD lesions with RSPO2/3 fusions or RNF43 alterations." (PMID 31563876, 2020). "WNT pathway blockade with porcupine inhibitors is effective in RSPO3-rearranged CRC preclinical models and clinical trials in patients with RSPO2/3-fusion-positive tumours of any histological origin are ongoing (NCT01351103)." (PMID 31097696, 2019). "Because our fusion genes did not alter the RSPO2 expression cassette, gene modifications only affected RSPO2 expression and secretion in tumor tissues." (PMID 30250044, 2018). "In screening 207 PDX models with tumor samples of Asian cancer patients, we have found that about 1.4% of tumor samples contain RSPO2 fusion." (PMID 30250044, 2018). "In summary, we have identified novel RSPO2 fusions and demonstrated that CGX1321 has remarkable efficacy in reducing tumor growth in PDX mouse models containing RSPO2 fusion." (PMID 30250044, 2018). "The GA3055 tumor contained an HNF4G-RSPO2 fusion between RSPO2 exon 2 and HNF4G exon 3 (NM_001330561.1)." (PMID 30250044, 2018). "Our study indicated RSPO2 was significantly down-regulated in READ and kept the line with the published research, which demonstrates RSPO2 functions as a tumor suppressor; over-expression of it inhibits CRC cell proliferation and tumorigenicity." (PMID 28350845, 2017). "Most importantly, both Rspo2 and Rspo3 fusions represent druggable cancer drivers, as the tumours are sensitive to Wnt-targeted therapy with a meaningful therapeutic window." (PMID 28695896, 2017). "Altogether, our study provides direct evidence that endogenous Rspo2 and Rspo3 chromosome rearrangements can initiate and maintain tumour development, and indicate a viable therapeutic window for LGK974 treatment of RSPO-fusion cancers." (PMID 28695896, 2017). "Since R-spondin sensitizes cells to Wnt ligands through inhibiting ZNRF3/RNF43, tumor cells harboring RSPO2/RSPO3 translocations should be sensitive to either direction inhibition of RSPO2/RSPO3 or inhibition of Wnt ligand secretion by porcupine inhibitors." (PMID 27338477, 2016). "WNTpositive CSCs in orthotopic PDAC tumor sections were surrounded by RSPO2 (unpublished data), and RSPO2 expression significantly correlated with EMT inducer ZEB1 in tissue microarrays of PDAC patients." (PMID 26622937, 2015). "In the validation cohort, RSPO2 positivity strongly correlated with LGR5 tumor expression (p < 0.0001), with 80% of LGR5-positive tumors also staining positive for ligand RSPO2." (PMID 26416247, 2015). "In all, 4/16 of the neoplasia expressed Fgf3, 7/16 expressed Wnt-1, 6/16 expressed Wnt10b, and 11/16 expressed Rspo2." (PMID 23866257, 2013). "Therefore, RSPO4 shares similarities with RSPO2 in the mechanism of tumor suppression but with obvious difference." (PMID 41522353, 2026). "In PC, RSPO2 amplified tumors harbored multiple clinical measurements of tumor malignancy." (PMID 40711886, 2025). "In conclusion, our results have explored the potential involvement of DNA methylation as a driving mechanism of CRC and revealed a plausible functional role of epigenetic repression in certain tumour suppressor genes, such as RSPO2, in maintaining the viability of tumour cells." (PMID 37612734, 2023). "High levels of RSPO2 are detected in these tumours, whilst immunohistochemical analysis of HCC tumours harbouring RSPO2 mutations showed both strong nuclear β-catenin and glutamine synthetase staining, indicating a strong WNT pathway activation in these tumours." (PMID 37048063, 2023). "Inhibition of Src activity attenuated RSPO2-induced EGFR/Akt phosphorylation, whereas the suppression of Akt activity largely reduced the promotive effect of RSPO2 on cell proliferation, suggesting that RSPO2-induced Src/Akt activation mainly accounts for tumor growth." (PMID 36217544, 2022).
tumor (continued). "Inhibition of FAK or Src also partially impaired RSPO2-promoted cancer cell proliferation and migration, respectively, indicating that FAK/Src mutual activation in RSPO2-overexpressing tumor cells may synergistically promote tumor progression." (PMID 36217544, 2022). "In addition, mice injected subcutaneously with A2780 cells (with a high level of RSPO2 expression) harboring shRSPO2 developed a markedly decreased tumor burden compared to that in mice injected with shNC control cells." (PMID 36217544, 2022). "The RSPO2 anti-oncogenic role on CRC growth depends on the LGR5 presence on neoplastic cells: RSPO2 may function as a tumor suppressor by negatively regulating WNT signaling through a LGR5-dependent manner." (PMID 33562604, 2021). "RSPO2 can block binding of Wnt5A to Fzd7 receptor to antagonize tumor cell migration." (PMID 31655798, 2019). "Moreover, R-spondin-2 and olfactory receptor 52R1 were also detected in 80% of T2 tumor samples, but R-spondin-2 was also found in 50% of the samples of patients with T3 + T4 tumors, and olfactory receptor 52R1 was found in 25% of the samples of patients in this group." (PMID 37761972, 2023). "RSPO2's role in cancer is unclear; it could be an oncogene or a tumor suppressor." (PMID 35281864, 2022). "Hence, RSPO2 has also been attributed tumor suppressive activities in CRC in some reports." (PMID 34663878, 2021). "RSPO2 inhibits tumor cell migration, implying it might also have therapeutic effects in FPA." (PMID 31655798, 2019). "However, RSPO2 functions as a tumor driver or suppressor in CRC is still controversial." (PMID 28350845, 2017). "Interestingly, RSPO2/3 translocations have also been identified in other tumor types." (PMID 27338477, 2016). "Overexpression of RSPO2 in A2780 and OVCAR3 tumor cells markedly enhanced their growth capability as evaluated by MTT and colony formation assays." (PMID 36217544, 2022). "In contrast, knockdown of RSPO2 markedly suppressed the migration and invasion of A2780 and OVCAR3 tumor cells." (PMID 36217544, 2022). "Tumor growth- and cell survival-related pathways, such as MAPK and PI3K/Akt, were profoundly enriched and upregulated in RSPO2-overexpressing A2780 cells." (PMID 36217544, 2022). "siRNA and shRNA-mediated RSPO2 knockdown both significantly reduced cell growth of A2780 and OVCAR3 tumor cells." (PMID 36217544, 2022). "Among the four mutated genes (i.e., NCOR1, MUC16, MUC4, and RSPO2), NCOR1, MUC16, and MUC4 were reported to have been directly involved in modulating tumor microenvironment and thereby mediating drug resistance." (PMID 33504001, 2021). "In this line, our group has analyzed RSPO2 and RSPO3 mRNA expression in a set of 86 tumor tissue samples representative of different STS subtypes from the University Hospital Son Espases and the Spanish Group for Research on Sarcoma (GEIS)." (PMID 34771683, 2021). "In CR3056 tumor samples, the PVT1-RSPO2 exon 3 fusion contained the fusion point starting at the exon 3 region of RSPO2, which results in frameshift and premature stop codon." (PMID 30250044, 2018). "Here, we analyzed various types of RSPO2 fusions in PDX tumors and confirmed their driving effects in tumor progression." (PMID 30250044, 2018). "Our study shows that indeed, endogenous RSPO2 and RSPO3 rearrangements can initiate tumour growth in the intestine, but that they drive disease on a molecularly distinct course compared to Apc mutations." (PMID 28695896, 2017). "We observed that RSPO2 and its receptor, GPR48/LGR4, were expressed in normal thyroid gland and at higher levels in in PTCs, particularly in patients with regional tumor progression, including lymph node (LN) metastasis." (PMID 29383135, 2017). "In an attempt to simulate these contextual cues of the tumor microenvironment (TME), extrinsic addition of RSPO2 significantly increased the WNTpositive CSC pool, drove EMT, and activated ERK1/2 signaling." (PMID 26622937, 2015).
tumor (continued). "We confirmed the presence of active virus in Mtv-1/NIV infected tissues and using quantitative reverse transcription PCR (qRT-PCR) found that Mtv-1/NIV induced neoplasms (tumors and hyperplasia) commonly expressed the core CIS genes Wnt1, Wnt10b, Rspo2, Fgf3." (PMID 23866257, 2013). "Despite the implications of RSPO2 as a pro-tumor Wnt signaling regulator, there is no current effort to directly disrupt RSPO2 signaling in the clinical setting." (PMID 40711886, 2025). "Immunohistochemical analysis of paired tumor and nontumor tissue specimens showed that RSPO2 was more intensely and extensively expressed in tumor tissues than in normal tissues." (PMID 36217544, 2022). "Manipulating the expression of RSPO2 did not change the levels of Frizzled 6/7, nor did the Frizzled inhibitor niclosamide abolish the tumor-promoting effect of RSPO2 in two cells." (PMID 36217544, 2022). "Among the R-spondin genes, RSPO2 expression is clearly correlated with TCF7L1, but only in normal tissue, while RSPO3 expression is less strongly correlated with TCF7L1, both in normal and tumor tissue." (PMID 32403323, 2020). "We show that both Rspo2 and Rspo3 fusion events are sufficient to initiate hyperplasia and tumour development in vivo, without additional cooperating genetic events." (PMID 28695896, 2017). "The expression of Rspo2 and Rspo3 in colon tumor samples, containing the fusions, was elevated compared with the tumor samples lacking R-spondin fusions." (PMID 26379625, 2015). "Interestingly, little to no expression of RSPO1 and RSPO2 were found in these cell lines, suggesting that their expression in primary tumors was most likely from stromal or other non-tumor cells." (PMID 39065640, 2024). "Nevertheless, it should be noted that RSPO2 and LGR4 are not globally expressed in all tumor cells in the Wnthigh GBM xenografts, suggesting heterogeneous property of GBM cells and their distinctive of β-catenin activity." (PMID 30337838, 2018).
cancer (31 papers, 2012 to 2025). A tumor composed of atypical neoplastic, often pleomorphic cells that invade other tissues. "RSPO2 is often mutated in cancers and gene fusions regulated by new promoters often lead to RSPO2 overexpression." (PMID 30250044, 2018). "There are four members of the RSPONDIN family, of which RSPO2 is most frequently mutated in cancer." (PMID 37048063, 2023). "According to research, RSPO2 has been linked to cancer by the Wnt/β-catenin signaling pathway and may be carcinogenic in some cases." (PMID 35281864, 2022). "Indeed, mutations of RNF43/ZNRF3 and recurrent translocations of RSPO2/RSPO3 have recently been identified in various cancers." (PMID 27338477, 2016). "RSPO2 is a secreted glycoprotein that stimulates Wnt/β-catenin signaling and functions as a cancer driver." (PMID 40076569, 2025). "Beginning with a pan-cancer analysis from The Cancer Genome Atlas (TCGA) (N = 10,967), we found that RSPO2 alterations were present in 5% of cancer patients, with the majority being gene amplifications." (PMID 40711886, 2025). "Our findings of increased RSPO2 expression in the worst-prognosis clusters further support its role as a cancer driver, particularly in BC subtypes with aggressive phenotypes." (PMID 40076569, 2025). "Across cancers, RSPO2 amplifications exhibited the worst outcomes in both disease-free and progression-free survival (HR: 1.58 and 1.21, p-value: 0.0003 and 0.0105 CI: 0.799–2.361 and 0.849–1.571, respectively)." (PMID 40711886, 2025). "To confirm the binding profile difference of monovalent and bivalent RSPO2 furin domain forms, we examined the binding of the two forms on cancer cell lines that express either LGR4 or LGR5 endogenously." (PMID 37402772, 2023). "RSPO2, a new cancer inhibitor gene, was able to prevent HCC from proliferating and invading the MAPK signaling pathway." (PMID 36645115, 2023). "The mRNA expression of RSPO2 in cancer cells was generally higher than that in ovarian epithelial IOSE80 cells." (PMID 36217544, 2022). "Our data showed that knockdown of DKK1 in cancer cells successfully reduced the RSPO2- or RANKL-induced OP recruitment and osteoclast number and activity in tibiae and spines." (PMID 34847079, 2022). "Through interaction with its ligand R-spondin 2, Lgr5 functions as a negative regulator of Wnt-signaling to suppress the cancer proliferation and metastasis." (PMID 31901081, 2020). "We also investigated the RSPO2–GPR48/LGR4 signaling axis in Nthy-ori3-1 cells, which express lower endogenous levels of RSPO2 than cancer cells." (PMID 29383135, 2017). "Identification of RSPO2/RSPO3 translocations in cancer provides not only an attractive target for Wnt pathway inhibition using antibody approaches but also an intuitive predictive biomarker for RSPO2/RSPO3 antibodies." (PMID 27338477, 2016). "However, RSPO2 amplification rates supersede each of the other family members in PC and across cancer types." (PMID 40711886, 2025). "Altogether, RSPO2 amplifications exhibited worse outcomes across cancer and in PC." (PMID 40711886, 2025). "It is important to note that whilst there have been promising results treating RNF43 or RSPO2/3 mutant cancers with porcupine inhibitors, one on-target side effect of these drugs is a loss of bone density since WNT signalling plays an important role in bone homeostasis." (PMID 37048063, 2023). "Moreover, knockdown of LGR4 in A2780 and OVCAR3 cells largely antagonized the growth promotive effect of RSPO2 and partially impaired the RSPO2-induced cancer cell migration." (PMID 36217544, 2022). "Furthermore, we showed that RSPO2 promoted the metastatic spread of cancer cells in an orthotopic ovarian xenograft model and that these phenotypes were primarily ascribed to the activation of FAK/Src signaling pathways." (PMID 36217544, 2022). "Furthermore, knockdown of integrin αv/β3 also reduced the promotive effects of RSPO2 on cell adhesion and migration and partially blocked RSPO2-enhanced cancer cell growth." (PMID 36217544, 2022).
cancer (continued). "Taken together, these findings suggest that the role of RSPO2 in tumorigenesis is complex and that its functions may be dependent on the type of cancer, the presence of receptors, and the cellular context." (PMID 36217544, 2022). "Our data show that Wnt pathway inhibition could provide an effective treatment for cancers containing RSPO2 fusion." (PMID 30250044, 2018). "R-Spondin 2 (RSPO2), a critical and novel enhancer of preexisting WNT signals that binds to receptors of the leucine-rich repeat-containing G-protein coupled receptor (LGR) family, enhanced cancer stemness in susceptible PDAC cells." (PMID 26622937, 2015). "RSPO2 might also enrich CSCs by regulating Lgr5 expression in cancer cells." (PMID 28404917, 2017). "Based on the ALAN quantitative outputs, RSPO2 behaved similarly to EMT-related genes and FGFR1/2, but exhibited opposing behavior with AR regulatory genes and MYC, a pan-cancer oncogene." (PMID 40711886, 2025). "We further integrated our methylation results with RNA-seq data, and we identified 11 genes, including six related to immune functions (AHR, LRFN5, NTRK2, RSPO2, SAMSN1, and TFEC), and three related to cancer (SLC12A5, SORCS1, and TP63)." (PMID 39795948, 2024). "This analysis identified new contexts for fusion transcripts leading to overexpression of cancer genes located at the fusion 3′ end, such as NUTM1, RSPO2/3, and ROS1." (PMID 31097696, 2019). "RNF43, ZNRF3, RSPO2 or RSPO3 alterations in breast, colorectal, gastric, pancreatic and other cancers activate the Wnt/β-catenin signaling." (PMID 29312609, 2017). "The multimodal function may also pan out in cancer, notably colorectal (CRC) where RSPO2 is thought to act merely as Wnt agonist but where FGF and BMP signaling are also implicated." (PMID 38307837, 2024). "For instance, miR-196b-5p displays high expressions, whereas its target gene RSPO2 (R-Spodin 2) is expressed low in the cancer tissues and normal in para-cancer tissues, promoting proliferation and migration and invasion of LUAD." (PMID 35711943, 2022). "We provide evidence that among the 4 members, only RSPO2 enhanced the recruitment of OPs, suggesting that the 4 members of the RSPO family have tissue-specific and spatiotemporally regulated functions in regulating cancer progression." (PMID 34847079, 2022). "We identified HBV integrations with high integration allele fractions in tumors in seven non-recurrent cancer-related genes, including GAS7, NSP, RSPO2, NRG1, PRDM16, ARID1B, and AFF1." (PMID 33557409, 2021). "Lgr5 and its ligand, RSPO2, might have the same effect on enriching and maintaining ESCC cancer stem cells." (PMID 28404917, 2017).